BTG1 (BTG anti-proliferation factor 1)
Diseases named in the same sentence as BTG1 in open-access papers (continued):
Sharing a sentence is not in itself a finding about the gene and the disease.
Down syndrome (1 paper, 2024). "Nonetheless, two other studies ⎼ one carried out with 116 patients with Down syndrome and ALL, and the other including 533 B-ALL patients ⎼ demonstrated that isolated BTG1 deletion was not able to impact the prognosis of the patients." (PMID 39095315, 2024).
endometriosis (1 paper, 2019). The growth of functional endometrial tissue in anatomic sites outside the uterine body. "Eutopic endometrium of the control group (1.95 ± 0.35) displayed significantly higher BTG1 mRNA expression than both eutopic (1.12 ± 0.14; p = 0.048) and ectopic (0.81 ± 0.22; p = 0.004) endometrium of the endometriosis group." (PMID 31324015, 2019). "In contrast, BTG1 immunostaining was patchy and markedly reduced in the eutopic endometrium of the endometriosis group." (PMID 31324015, 2019). "Our data suggest that BTG1 regulates cellular apoptosis via the intrinsic pathway in HESCs, thus affecting the pathogenesis of endometriosis." (PMID 31324015, 2019). "BTG1 mRNA expression level of eutopic and ectopic endometrium of endometriosis group were significantly lower than that of the eutopic endometrium of the control group." (PMID 31324015, 2019). "Although BTG1 is a known anti-proliferative gene, the role of BTG1 in the pathophysiology of endometriosis has remained unclear." (PMID 31324015, 2019). "BTG1 staining intensity in eutopic and ectopic endometrium of the endometriosis group was markedly decreased compared with that in the eutopic endometrial tissue samples of the control group." (PMID 31324015, 2019). "In this study, we observed that BTG1 expression was significantly reduced in ectopic and eutopic endometrial tissues of patients with endometriosis." (PMID 31324015, 2019). "In conclusion, our data suggest that downregulation of BTG1 plays an important role in the pathogenesis of endometriosis." (PMID 31324015, 2019). "Our observations suggest that reduced expression of BTG1 facilitates proliferation and migration of HESCs and suppresses their apoptosis, resulting in the progression of endometriosis." (PMID 31324015, 2019). "Nevertheless, a significant reduction in BTG1 expression was observed in ectopic and eutopic endometrium of patients with endometriosis." (PMID 31324015, 2019). "BTG1 mRNA and protein expression was evaluated in eutopic and ectopic endometrium of 30 patients with endometriosis (endometriosis group), and in eutopic endometrium of 22 patients without endometriosis (control group)." (PMID 31324015, 2019). "We observed that BTG1 expression was significantly reduced in ectopic and eutopic endometrial tissues of patients with endometriosis." (PMID 31324015, 2019). "In conclusion, we demonstrated that downregulation of BTG1 could play an important role in the progression of endometriosis." (PMID 31324015, 2019). "The role of BTG1 in endometrial cellular proliferation and the precise molecular mechanisms of BTG1 function in the pathogenesis of endometriosis remain unclear." (PMID 31324015, 2019). "The aim of this study was to determine the role of BTG1 in the pathogenesis of endometriosis." (PMID 31324015, 2019). "We observed that the expression levels of BTG1 was reduced in endometriosis." (PMID 31324015, 2019). "Third, the majority of patients had moderate-to-severe endometriosis; therefore, we failed to investigate the association between BTG1 expression status and the severity of endometriosis." (PMID 31324015, 2019). "Using immunohistochemistry, we investigated BTG1 protein expression in eutopic and ectopic endometrial tissue samples in patients with and without endometriosis." (PMID 31324015, 2019). "In this study, we investigated BTG1 expression in eutopic and ectopic endometrial tissue samples obtained from patients with or without endometriosis." (PMID 31324015, 2019). "In both groups, differences in BTG1 mRNA expression between proliferative and secretory phases were not statistically significant, although the endometriosis groups exhibited lower expression levels than the control group in both the proliferative and secretory endometrial tissue samples." (PMID 31324015, 2019).
Insulin resistance (1 paper, 2024). Increased resistance towards insulin, that is, diminished effectiveness of insulin in reducing blood glucose levels. "So when mice with insulin resistance are infected by adenovirus, the high expression of BTG1 increases the sensitivity of cells to insulin, similar to that observed in wild-type mice." (PMID 38357499, 2024). "Moreover, transgenic mice with high levels of expression of BTG1 were insensitive to insulin resistance induced by a high-carbohydrate diet." (PMID 38357499, 2024).
intestinal-type carcinoma (1 paper, 2015). "Moreover, BTG1 was more expressed in elder men than younger women patients, possibly due to its overexpression in intestinal-type carcinoma commonly seen in the former population." (PMID 26050197, 2015).
keloid (1 paper, 2024). An irregularly shaped, elevated mark on the skin caused by deposits of excessive amounts of collagen during wound healing. "A fibroblast-related diagnostic model for keloid based on a six-gene signature (CCNB1, EGFR, E2F8, BTG1, TP63, and IGF1) was proposed, showing high predictive accuracy in keloid diagnosis." (PMID 39157347, 2024). "•CCNB1, EGFR, E2F8, BTG1, TP63, and IGF1 were associated with keloids." (PMID 39157347, 2024). "The established model based on CCNB1, EGFR, E2F8, BTG1, TP63, and IGF1 showed good performance and may be useful for keloid diagnosis." (PMID 39157347, 2024). "In the training dataset, the expression levels of CCNB1, EGFR, E2F8, BTG1, as well as TP63 were remarkedly lower in the keloid samples than in the control samples (P < 0.05); however, the expression of IGF1 was evidently enhanced in the keloid samples elative to the control samples (P < 0.05)." (PMID 39157347, 2024). "In comparison to levels in control tissues, the expression levels of CCNB1, EGFR, BTG1, as well as TP63 were evidently lower in the keloid tissues (P < 0.05), while the expression levels of E2F8 as well as IGF1 were evidently higher in the keloid tissues (P < 0.05)." (PMID 39157347, 2024).
lipoma (1 paper, 2017). A benign, usually painless, well-circumscribed lipomatous tumor composed of adipose tissue. "PFN2 (profilin 2), BTG1 (BTG anti-proliferation factor 1), LPP (LIM domain containing preferred translocation partner in lipoma) and CDK6 (cyclin dependent kinase 6) came to prominence as significant genes that have important effects in the cancer progression." (PMID 28981542, 2017).
lymphocytic leukemia (1 paper, 2026). "PC3/Tis21/BTG2 and BTG1, prototype members of the BTG/Tob family, are antiproliferative transcriptional cofactors discovered 35 years ago as genes induced by nerve growth factor and phorbol 12-myristate 13-acetate or associated with lymphocytic leukemia." (PMID 42080092, 2026).
lymphoplasmacytic lymphoma (1 paper, 2019). A clonal neoplasm of small B-lymphocytes, lymphoplasmacytoid cells, and plasma cells involving the bone marrow, lymph nodes, and the spleen. "Finally, BTG1 copy number alterations are detected with a high frequency in lymphoplasmacytic lymphoma cases, leading to speculation that BTG1 loss may contribute to the pathogenesis of this non‐Hodgkin lymphoma subtype." (PMID 30350856, 2019).
malaria (1 paper, 2022). Malaria is a serious and sometimes fatal disease caused by a parasite that commonly infects a certain type of mosquito which feeds on humans. "Genes in cluster 4, underrepresented in symptomatic malaria and upregulated by asymptomatic infection, included several genes encoding protein products mediating negative regulation of immune processes, such as the anti‐proliferative molecules BTG1 and NDRG2, as well as the checkpoint receptor CD83." (PMID 35475529, 2022).
malignant rhabdoid tumors (1 paper, 2021). "Additionally, combing LDC0000167 with the BRD4 inhibitors-JQ1 or iBET-762 against malignant rhabdoid tumors, down-regulated the anti-apoptotic genes MCL-1, BCL-6 and BTG1 as well as MYC and inhibited cell-proliferation and tumor growth in vitro and in vivo." (PMID 34062779, 2021).
rectal cancer (1 paper, 2017). A primary or metastatic malignant neoplasm that affects the rectum. "Five comparisons from Skrzypczak’s and TCGA datasets revealed that the expression of BTG1 was reduced in both colon and rectal cancer compared with normal tissues." (PMID 28922388, 2017).
renal fibrosis (1 paper, 2023). A final common manifestation of a wide variety of chronic kidney diseases characterized by glomerulosclerosis and tubulointerstitial fibrosis. "Moreover, comprehending the roles of VEGFA and BTG1 in renal fibrosis may open the door to personalized treatment approaches." (PMID 37949939, 2023).
Sepsis (1 paper, 2025). Sepsis is defined as life-threatening organ dysfunction caused by a dysregulated host response to infection. "Conversely the upregulated genes in sepsis Th1 cells showed enhanced endopeptidase activity (GAPDH; 0.75log2FC) and angiogenesis related (XBP1, CXCR4, and BTG1; 0.93, 0.66, and 0.64log2FC, respectively) pathways." (PMID 41208955, 2025). "In contrast, sepsis Treg cells displayed four upregulated genes (RGS1, HLA-DPA1, BTG1, and GAPDH; 1.25, 1.02, 0.44, and 0.43log2FC, respectively)." (PMID 41208955, 2025).
squamous cell carcinoma (1 paper, 2022). A carcinoma arising from squamous epithelial cells. "In TCGA data, BTG1 expression was higher in squamous cell carcinoma than adenocarcinoma, in male than female cancer patients, and in elder than younger cancer patients (p < 0.05)." (PMID 36339000, 2022). "BTG1 expression was higher in pulmonary squamous cell carcinoma than in adenocarcinoma, which provided another evidence that squamous cell carcinoma but not adenocarcinoma showed higher BTG1 expression than normal tissue." (PMID 36339000, 2022).
tumor (55 papers, 2014 to 2026). "We expected that the increase of proliferation of GCPs observed in the EGL of Ptch1+/+/Btg1KO mice at P7 caused by Btg1 deletion would lead in Ptch1+/−/Btg1KO cerebella to an increase of Ptch1+/− cells, which are prone to tumor development." (PMID 32231994, 2020). "Thus, in this study, we tested if the loss of the Btg1-dependent control of GCP proliferation is able to increase the spontaneous tumor incidence in an Shh-MB model, crossing Btg1 knockout mice to Patched1 heterozygous (Ptch1+/−) mice." (PMID 32231994, 2020). "How tumor cells benefit from loss of BTG1 function remains to be elucidated." (PMID 26657730, 2016). "Furthermore, low BTG1 mRNA expression is associated with poor outcome or tumor metastasis in several solid tumors." (PMID 26657730, 2016). "While there is ample data to support the notion that BTG1 is a negative regulator of proliferation in tumor cells, it remains unclear how BTG1 deficiency contributes to tumorigenesis." (PMID 26657730, 2016). "Among them, we selected seven genes associated to cell proliferation and apoptosis that resulted downregulated in tumor samples: BTG1, CCNG1, DMD, EDG1, SEMA3G, SYNPO2, TIMP2." (PMID 39984959, 2025). "It is observed that BTG1 was highly expressed in the tumor-infiltrating cluster NK1, with an intermediate level expressed in NK5." (PMID 40315330, 2025). "Another two tumor suppressor genes Btg1 and Nbl1 were also significantly upregulated following 4-OHA treatment." (PMID 37056757, 2023). "Then, we found that the protein expression of SLC16A2 was higher in BC tumor tissues, whereas that of BTG1 was higher in adjacent normal tissues by immunohistochemical staining assay." (PMID 36998462, 2023). "BTG1 is a well-characterized tumor suppressor for both solid tumors and hematopoiesis and recently has been reported to have a novel role in genotoxic and integrated stress responses." (PMID 35774514, 2022). "It was reported that BTG1 overexpression inhibited tumor cell proliferation, metastasis, invasion, and promoted apoptosis." (PMID 36311764, 2022). "The most frequently mutated genes in the tumor tissue cohort were DTX1 (37%), CD79B (35%), BTG1 (30%), BTG2 (30%), and TMSB4X (30%)." (PMID 36280874, 2022). "Next, the correlations between plasma exosome-derived BTG-1 levels and tumor characteristics in NSCLC patients were assessed." (PMID 33531999, 2021). "Next, the correlations between plasma exosome-derived BTG-1 levels and tumor characteristics in patients with NSCLC were assessed." (PMID 33531999, 2021). "An antiproliferative protein gene BTG1 was highly expressed in infiltrating B cells of the early CRC tumor." (PMID 33463049, 2021). "With regard to tumor suppressors, DSV–iECs showed an equal divide: 2 up-regulated (mutations: DNMT3A; CNAs: FANCA) and 2 down-regulated (CNAs: IRF1, BTG1) genes." (PMID 32934781, 2020). "As a tumor suppressor, BTG1 overexpression is observed in the G0/G1 phases of the cell cycle and its down-regulation once cell progression through G1." (PMID 33330092, 2020). "In fact, Btg1 expression appears to regulate the balance between proliferation and apoptosis in MB tumor formation." (PMID 32231994, 2020). "One of the well-known cell cycle regulators, BTG1, functions as a tumor suppressor by keeping cell cycle at G0 phase and its expression is down regulated in multiple malignant tumors." (PMID 30787206, 2019). "In some of these cases decreased BTG1 expression appears to correlate with poor overall survival and tumor metastasis formation." (PMID 30350856, 2019).
tumor (continued). "A number of observations point to a tumor suppressive role for BTG1 and BTG2 in a range of malignancies, although in most examples, the exact mechanism by which BTG1 or BTG2 contribute to tumor development/progression requires further investigation." (PMID 30350856, 2019). "B-cell translocation gene 1 (BTG1), a translocation partner of the c-myc, is a tumor suppressor gene that promotes apoptosis and negatively regulates cellular proliferation and cell-to-cell adhesion." (PMID 31324015, 2019). "Sixty-three significant unique analyses revealed that the mRNA expression level of BTG1 varied with the type of tumor." (PMID 28922388, 2017). "We conclude from these experiments that, across different cell lineages, tumor suppressor BTG1 acts as an enhancer of ATF4 mediated stress responses, while a loss of BTG1 function promotes cellular survival in response to nutrient stress." (PMID 26657730, 2016). "The tumor volume of BGC-823 cells xenograft was larger than that of BTG1 transfectants by gross appearance, CT scanning and ruling respectively (p < 0.05)." (PMID 26050197, 2015). "Changes of its expression levels render tumor cells sensitive to radiation due to the role of BTG1 in cell cycle progression." (PMID 25115181, 2014). "In addition, the plasma-exosome-derived BTG-1 levels have been related to tumor diameter, stage, tumor metastasis, the degree of tumor differentiation, and abnormal CEA levels, in accordance with previous findings of BTG-1 expression in other cancers." (PMID 36230852, 2022). "In our study, one FL case (Case-16) had the BTG1 p.E46D and B2M p.Q22* mutations specifically in plasma cfDNA but not in the tumor tissue DNA of the same FL patient." (PMID 35795062, 2022). "This shows that the BTG1 gene plays a similar role to tumor suppressor genes in the occurrence and development of various cancers and may be a potential tumor biomarker and therapeutic target." (PMID 35498539, 2022). "Moreover, low plasma exosome-derived BTG-1 levels were related to tumor diameter, stage, metastasis, the degree of tumor differentiation, and abnormal carcinoembryonic antigen (CEA) levels." (PMID 33531999, 2021). "Moreover, BTG-1 plays important roles in promoting apoptosis and suppressing the invasion and metastasis of tumor cells." (PMID 33531999, 2021). "BTG2 and BTG1 are tumor-suppressor genes and members of the human BTG/TOB family." (PMID 33777778, 2021). "Furthermore, plasma exosome-derived BTG-1 levels were negatively related to tumor diameter, stage, metastasis, the degree of tumor differentiation, and abnormal CEA levels, thus leading to a poor 3-year DFS and OS." (PMID 34595207, 2021). "Also in MB lesions and in tumor cells, i.e., in Ptch1+/− background, the deletion of Btg1 highly increases apoptosis." (PMID 32231994, 2020). "Through GEPIA, we obtained the relative expression of BTG1 in each tumor and normal tissues." (PMID 33041670, 2020). "In addition, knockdown of BTG1 reverses effects of PUM2 knockdown on tumor cell proliferation and migration." (PMID 30787206, 2019). "BTG1 reportedly is a mediator of B-cell differentiation and may act as a tumor suppressor because of its inhibitory effects on proliferation and cell cycle progression." (PMID 29721160, 2018). "In xenograft models, BTG1 overexpression might suppress tumor growth, blood supply and proliferation, and induce apoptosis and autophagy." (PMID 27447746, 2017). "Since the decrease in tumor surface expression of BTG1 and PEDF has been associated with increased cancer growth and metastasis, tumor cell exosomal shedding of these proteins obviously decreases the cell surface content of these molecules, which benefits the tumor." (PMID 26601108, 2015).